DAPK1 (death associated protein kinase 1)
Diseases named in the same sentence as DAPK1 in open-access papers (continued):
Sharing a sentence is not in itself a finding about the gene and the disease.
cancer (continued). "Inhibition of DNA methylation by drugs such as dexitabine can restore the expression of NTN1 and DAPK1 in cancer cells with low expression of Netrin-137,38,68." (PMID 32251318, 2020). "Whereas 75% (24 out of 32) of the cancer tissues was positive for DAPK1, only 13% (4 out of 32) of the controls was positve." (PMID 32566040, 2020). "In summary, augmented DAPK1 expression in cancers can be interpreted as a stress response survival mechanism to remediate ongoing deleterious events in the cells orchestrated by carcinogenesis." (PMID 32566040, 2020). "Downregulation of DAPK1 by methylation in its promoter region is detected in various cancers, including pancreas, lung, and head and neck." (PMID 31336860, 2019). "Dysregulation of DAPK1 expression or activity is often related to multiple diseases including cancer and stroke." (PMID 30999631, 2019). "The silencing of DAPK1 by promoter hypermethylation has been long linked to CC, but the established data showed a varied range of DAPK1 promoter hypermethylation rates (24–100%) in cancer tissues and inconsistent association results." (PMID 30065752, 2018). "DAPK1 methylation detection exhibits a promising ability to discriminate CC from cancer-free controls." (PMID 30065752, 2018). "DAPK1 has been shown to play important role in apoptosis and autophagy to suppress cancer progression." (PMID 28388658, 2017). "Our results showed that DAPK1 methylation was unrelated to cancer differentiation, T stage, N stage, or M stage in gastrointestinal cancer." (PMID 28934284, 2017). "This has led to the development of DAPk1 and DAPk2 based fusion proteins for the treatment of cancer." (PMID 28976934, 2017). "Results described in this manuscript propose that the inhibition of DNA methylation by drugs such as decitabine restores the expression of both NTN1 and DAPK1, in netrin‐1‐low cancer cells." (PMID 27378792, 2016). "The inhibition of DNA methylation by drugs such as decitabine restores the expression of both NTN1 and DAPK1 in netrin‐1‐low cancer cells." (PMID 27378792, 2016). "Hypermethylation of DAPK1 has been frequently reported in various cancers types, including colon, head and neck, urinary bladder, lung, B cell lymphoma and ovary." (PMID 26267895, 2015). "Conversely, DAPK1, has been shown to be the target of repression in a number of cancers, including AML, breast cancer, and PCa [Submitted]." (PMID 26097870, 2015). "Reduced expression and aberrant methylation of DAPK1 has been reported in numerous human cancers, including GC." (PMID 25202403, 2014). "The low expression of DAPK1 was regarded as principlally an anti-apoptotic phenomenon, which has been previously observed in many cancer cells." (PMID 24037645, 2013). "DAPK1 gene expression was significantly lower in the two studied cancer cell lines in comparison with the non-cancer endothelial cells." (PMID 24037645, 2013). "DAPK1 was statistically significantly downregulated in both studied cancer cells, in particular LN18 (FC = −27.7, p = 0.006)." (PMID 24037645, 2013). "Moreover, numerous studies have documented that DNA methylation suppresses DAPK1 gene expression, particularly in cancer cells." (PMID 40918124, 2025). "Several studies showed that DAPK1 is involved in both the early and late stages of cancer." (PMID 39057063, 2024).
cancer (continued). "DAPK1 is known to regulate not only cancer cells but also stromal cells." (PMID 39057063, 2024). "In the context of cancer, extensive research has been conducted on the role of DAPK1." (PMID 38463514, 2024). "Significant hypermethylation has been observed near the DAPK1 promoter in 20 cancer types." (PMID 39057063, 2024). "DAPK-1 may have the potential to enhance cancer treatment by inhibiting the oncogenic activity of Pin1." (PMID 39081443, 2024). "Furthermore, inhibiting DAPK1 enhances cancer stem cell (CSC) stemness and the epithelial-mesenchymal transition (EMT) process, with the DAPK1-ZEB1 axis potentially intersecting the TGF-β and WNT pathways and influencing both CSCs and EMT processes." (PMID 38802881, 2024). "The results obtained to date indicate the potential of DAPK1 as a regulator of cancer metastasis." (PMID 39057063, 2024). "Interestingly, DAPK1 has been reported to interact with and activate the pyruvate kinase isoform M2 in cancer cells in a kinase activity-independent manner." (PMID 38195518, 2024). "Therefore, it will be interesting to understand how the cell death function of DAPK-1 contributes to its role in cancer." (PMID 37372454, 2023). "Additionally, CYP1B1 depletion was shown to reduce the growth, invasion, and migration of cancer cells through the upregulation of cell division cycle 20 homolog (CDC20) and down-regulation of death-associated protein kinase-1 (DAPK1)." (PMID 38001897, 2023). "In addition, overexpression of DAPK1 was reported in many cancers, which suggests the possibility of AB1 inducing changes to the genome of MCF10A cells, inducing cancer." (PMID 36233156, 2022). "The expression of DAPK1 decreased in cancer cells treated with TNFα and increased in cells treated with NEC-1, showing that DAPK1 may influence the progression of cancer by inhibiting necroptosis." (PMID 36505813, 2022). "Among those genes, only DAPK1 and SYTL2 have been implicated in cancers." (PMID 35487942, 2022). "The negative association of DAPK1 mRNA expression with SI and DAPK1 protein levels with stem cell marker expression is indicative of the role of DAPK1 in cancer stemness." (PMID 34831219, 2021). "The role of DAPK1 in carcinogenesis could differ according to the type of cancer cell and the extent and the progression of cancer." (PMID 34831219, 2021). "In addition to cancer, the expression of DAPK1 was also regulated by non-coding RNAs in numerous other diseases." (PMID 34422899, 2021). "Additionally, hypermethylation of DAPK1 has been a prognostic indicator in patients with various cancers." (PMID 34831219, 2021). "DAPK1 is a tumour suppressor protein down-regulated in many cancer types." (PMID 34696474, 2021). "In the early stage of carcinogenesis, DAPK1 could inhibit cancer cell proliferation by regulating sensitivity to an apoptosis-related signaling pathway." (PMID 34831219, 2021). "In late cancer, DAPK1 can inhibit cell movement and adhesion by interfering with integrins." (PMID 34422899, 2021). "As the activity of the downstream ZIP kinase is critically required in several cancers including prostate, colon and lung cancers, inhibitors of the upstream DAPK1 activity could be beneficial for the treatment of multiple types of cancer." (PMID 31809612, 2020). "However, the correlation between CSF1R/DAPK1 signalling pathways and cancer progression provides motives to reprofile them against cancer therapy." (PMID 31809612, 2020). "DAPK1 is frequently downregulated in cancer contributing to disease progression." (PMID 31766427, 2019). "However, the precise relationship between DAPK1 and TAp63 in modulating apoptosis in cancer is unclear, and the autophagy-related signaling pathway regulated by TAp63 in cancer needs to be investigated." (PMID 31336860, 2019).
cancer (continued). "Expression of DAPK1 is often lost in cancers due to DNA methylation of the DAPK1 gene." (PMID 30999631, 2019). "DAPK1 is also mediated in anti-cancer drug resistance to 5-fluorouracil in endometrial adenocarcinoma cells, anti-epidermal growth factor receptor antibodies in lung cancer cells, gemcitabine in pancreatic cancer cells, and cisplatin in cervical squamous cancer cells." (PMID 30287790, 2018). "Among them, growing evidence of the role in DAPK1 in cancer processes are appearing." (PMID 30287790, 2018). "The death-associated protein kinase 1 (DAPK1) is an important regulator for apoptosis, when dysregulated may cause cancer." (PMID 28740751, 2017). "Down-regulation of DAPK1 expression through promoter methylation has been shown to be a prognostic factor in various types of cancer, including chronic lymphocytic leukemia, chronic myeloid leukemia, diffuse large B-cell lymphoma, cervical cancer, esophageal cancer and lung cancer." (PMID 28740751, 2017). "Moreover, the frequency of DAPK1 methylation was shown to gradually increased from precancerous lesions to cancer." (PMID 28934284, 2017). "DAPK1 is a novel 160 kd calmodulin-dependent serine/threonine kinase operating as a positive mediator of apoptosis, while apoptosis links to the development, progression, and metastasis of human cancer." (PMID 26267895, 2015). "Since DAPK1 is a positive mediator of apoptosis, the silencing of DAPK1 disabled the DAPK-mediated apoptosis and might then prompt metastasis in the cancer cells." (PMID 26267895, 2015). "The results of our epistasis analysis do not seem to support a role for Pin1/PINN-1 as an obligatory step downstream of DAPK/DAPK-1, as might be inferred from mammalian cancer studies." (PMID 25899010, 2015). "Findings indicate that grifolin might represent a promising candidate in the prevention and intervention of cancer by targeting DAPK1 signaling to induce cell cycle G1 phase arrest." (PMID 22582152, 2012). "However, the molecular mechanism involved in the regulation of cancer cells by DAPK1 remains unclear." (PMID 39057063, 2024). "Indeed, the majority of cancers commonly encountered have low expression of DAPK-1." (PMID 37372454, 2023). "SC can inhibit cell proliferation and induce cell apoptosis by decreasing MIB1‐mediated death associated protain kinase 1 (DAPK1) degradation, as well as enhance the chemosensitivity of TMZ to GBM, suggesting that SC might be a promising anti‐cancer agent for cancer therapy." (PMID 37346933, 2023). "Consequently, DAPK1 became a promising target protein for developing new anti-cancer agents." (PMID 36145271, 2022). "Since DAPK1 is part of rigidity sensing modules in fibroblasts, those cells can activate apoptosis on soft surfaces whereas DAPK1 is not linked to matrix rigidity when the sensory modules are missing cytoskeletal components and do not assemble as in cancer cells." (PMID 35927990, 2022). "Therefore, DAPK1 might be involved in the development of cancer and AD by regulating Pin1 function through its phosphorylation of Ser71." (PMID 32195254, 2020). "However, DAPK1 methylation was not correlated with the clinicopathological features of gastrointestinal cancer, but was associated with the N stage and cancer differentiation of GC." (PMID 28934284, 2017). "Moreover, since all studies included had a case-control design, it is not possible to clarify if DAPK1 promoter methylation is an early cancer-causing aberration or an effect of carcinogenesis." (PMID 26267895, 2015).
cancer (continued). "It is speculated that the proximal promoter of MLH1 is protected from heterochromatinization by insulators; which helps to explain that MLH1 is methylated in a lower fraction of tumors compared with other genes such as p16 and DAPK1 in cancer tissue DNA methylation profiling." (PMID 25606572, 2014). "However, unlike other hypermethylated genes, DAPK1 is localized in a genomic region that is never loss-prone in cancer." (PMID 19402918, 2009). "Although numerically modest, PTSPs were recurrent across samples and included products from cancer/immune genes (e.g., MITF, DAPK1, HLA-E), with synthetic-peptide validation and evidence of immunogenicity." (PMID 41293269, 2025). "As per the QPCR array data, Rapamycin is believed to induce apoptosis in cancer cells by altering the components of the extrinsic (CD40LG, DAPK1, LTA, TNFRSF21) and intrinsic (BIRC5, BNIP3) apoptotic pathways as well as the TP73 upstream modulator." (PMID 38276004, 2024). "DAPK1, a tumor suppressor of KIRC, is frequent lost in various types of cancer due to promoter hypermethylation." (PMID 37737260, 2023). "On the contrary, some core kinases and transcription factors involved in cancer such as CDK6, ERBB2, JAK1, DAPK1, FOXO1, and RXRA were highly expressed in S-III." (PMID 38143770, 2023). "Dihydroartemisinin, which was found to have antitumor activity in a variety of human cancers, induces cell apoptosis and autophagy-dependent cell death of CCA cells via the DAPK1-BECLIN1 pathway." (PMID 35126526, 2022). "Taken together, these results suggested that hnRNP A2B1 regulated the pre-mRNA splicing of pro-apoptosis genes (DAPK1, SYT7, and RNF128) and anti-apoptosis genes (EIF3H, TPPP3, and DOCK2), thus leading to the suppression of apoptosis of cancer stem cells." (PMID 33509274, 2021). "In contrast, we observed a significant decrease in cancer cell invasion in MDA-T32 and BCPAP cells after DAPK1 overexpression compared with controls (p < 0.001 and p < 0.001, respectively)." (PMID 34831219, 2021). "Simultaneous methylation of HIC1 + SFRP1 and DAPK1 + SOX1 exhibited sensitivity of 78.82 and 72.94%, respectively with specificity of 77.14% (AUC = 0.87 for both gene panels) for cancer detection." (PMID 34778370, 2021). "At the same time, pan-cancer analysis also shows that PPM1A, DAPK1, FBP1, PYHIN1, ALPL and SMCHD1 have significant amplification in PCa." (PMID 30867653, 2019). "Our results highlight DAPK1 as an anti-metastatic player in CRC and suggest DAPK1 as a potential predictive biomarker for this cancer type." (PMID 31772156, 2019). "Previous studies have reported that the DAPK1 promoter methylation is much more frequent in EC, GC, CRC cancer tissues than that in control tissue." (PMID 28934284, 2017). "An inverse correlation between the methylation of DAPK-1 and MLH1 was also identified in cancer tissues sampled from the middle third of stomach (coefficient, –0.41; p = 0.01)." (PMID 26810771, 2016). "Data obtained indicated that the 5′‐end CpGis of DAPK1 and NTN1 were methylated in the two cancer cell lines." (PMID 27378792, 2016). "In this context, previous studies have reported that DAPK1, a serine threonine kinase responsible for UNC5H‐induced apoptosis, is downregulated in various cancers." (PMID 27378792, 2016). "Conversely, in cells and tissues, DAPK1 and DAPK3 are downregulated in cancer contexts [18; Submitted]." (PMID 26097870, 2015). "Methylation of DAPK1 and RASSF1 genes is known to strongly contribute to carcinogenesis, metastasis and treatment failure in various types of cancer (Wong, Chang, Tang, Wei, & Kwong, 2002; Supic, Kozomara, Brankovic-Magic, Jovic, & Magic, 2009)." (PMID 27158284, 2015). "Methylation level of DAPK1, SLIT2, WIF1 and RARB genes combined distinguished cancer from normal cervical tissues and had significantly higher specificity compared to HPV detection and age alone." (PMID 25826459, 2015).
cancer (continued). "The first group of genes presented higher methylation levels in cancer tissues than in blood DNA (CDKN2A, APC, and DAPK1)." (PMID 26338139, 2015). "In total, 1,009 genes were prone to hypermethylation by this analysis in at least one type of cancer, including a number reported to be frequently hypermethylated in cancer (for example, APC, DAPK1, ESR1, GSTP1, SFRP genes and HOX genes)." (PMID 23034185, 2012). "The first group of genes displayed higher methylation levels in cancer tissues than in total blood DNA (p16, APC, 3OST2, DAPK1)." (PMID 22629410, 2012). "According to PubMeth, DAPK1, PYCARD, RB1, and TP73 are methylated in at least half of our fourteen cancer models." (PMID 19402918, 2009). "The expression and regulation of DAPK-1 are well-documented in different diseases, including cancer; however, there is a notable lack of information regarding the expression and regulation of s-DAPK-1 in various diseases, particularly in cancer." (PMID 40699815, 2025). "The absence of DAPK-1 expression in cancer cell lines has been proven to result from epigenetic suppression through DNA hypermethylation." (PMID 39081443, 2024). "How DAPK1 regulates CSCs and EMT in various cancer metastasis processes should be studied further." (PMID 39057063, 2024). "Although the function of autophagy was complex and often contradictory in cancers, but there were many evidences supporting that upregulation of ATG2B, ATG10, DAPK1 might contribute to good prognosis by promoting autophagy and apoptosis in ES." (PMID 35902797, 2022). "When analyzing the Receiver operating characteristic (ROC) curves for these genes we noted that, for the comparison of normal to cancer samples, MEG3 and MALAT1 had the highest Area Under the Curve (AUC), while when comparing normal vs. CIN, MLH1 and DAPK1 presented the highest AUC." (PMID 35682732, 2022). "Our results indicate that DAPK1 is an important regulator of cancer stemness by controlling metastasis rather than cell proliferation in thyroid carcinogenesis." (PMID 34831219, 2021). "DAPK1 is primarily involved in metastasis rather than proliferation in the later stages of cancer progression by modulating cancer cell adhesion, migration, invasion, and immune evasion." (PMID 34831219, 2021). "In contrast, APC, DAPK1, IGSF4, RARB, and TIMP3 genes were found to be methylated in cancer cells." (PMID 34552632, 2021). "About 88% (28 out of 32) of the nonbreast cancer tissue samples stained negative for DAPK1 compared to the 25% (8 out of 32) of the cancer tissue samples." (PMID 32566040, 2020). "Previous studies revealed that the expression of the DAPK1 protein does not match its expression of mRNA in some cancers, indicating that the regulation of DAPK1 expression is a complex process." (PMID 30999631, 2019). "CASP8, CCND1, DAPK1 and PSA are involved in pathways in cancer." (PMID 30867653, 2019). "In addition to the up-regulation of DAPK1 and FGFR3 in the cancer tissue, our analysis suggests following interactions." (PMID 23717626, 2013). "This was not valid for the low-differentiated carcinomas where DAPK-1 seems to be highly expressed." (PMID 39553125, 2024). "However, in some other studies, the frequency of DAPK1 methylation showed no obvious increase or even a reverse trend in cancer samples." (PMID 28934284, 2017). "Besides DAPK1, 5-Aza and DNMT1 antisense oligonucleotides are able to restore the sensitivity of cancer cells to IFN-triggered apoptosis despite the re-expression of the pro-apoptotic gene RASSF1A and XAF1 which are frequently silenced by epigenetic mechanisms." (PMID 21108789, 2010). "Importantly, the outcomes of reconstituting DAPk in target cells, for example by the recombinant immunokinase DK1KD-SGIII (a revised DAPk1), is marked by a robust catalytic activity (in inducing apoptosis) in vitro, in vivo, and in primary cells from cancer patients." (PMID 28976934, 2017).